CCDC77 (coiled-coil domain containing 77)
Synonyms: MGC13183
Tractability: PROTAC: UniProt records ubiquitination sites on it; ubiquitination databases record sites on it.
Gene: Protein-coding gene on chromosome 12 (389,273 to 442,644, forward strand). Ensembl gene ENSG00000120647.
Subcellular location (Human Protein Atlas): Nuclear membrane
Gene Ontology:
Cellular component: centrosome; membrane
Genetic constraint (gnomAD): Loss-of-function variants: 40 observed, 48.34 expected, observed/expected ratio (o/e) 0.83, 90% interval 0.64 to 1.08. The upper end of that interval is the gene's LOEUF score, 1.08, which puts it in group 4 of 6, group 1 being the genes least tolerant of losing a copy. Missense variants: 459 observed, 493.35 expected, observed/expected ratio (o/e) 0.93, 90% interval 0.86 to 1. Synonymous variants: 169 observed, 171.93 expected, observed/expected ratio (o/e) 0.98, 90% interval 0.87 to 1.12.
Homologues: Orthologues: chimpanzee CCDC77 (99% identical), macaque CCDC77 (90% identical), dog CCDC77 (86% identical), rabbit CCDC77 (83% identical), pig CCDC77 (81% identical), mouse Ccdc77 (81% identical), guinea pig CCDC77 (80% identical), rat Ccdc77 (78% identical), tropical clawed frog ccdc77 (53% identical), zebrafish ccdc77 (48% identical), tropical clawed frog ccdc77 (39% identical).
Diseases named in the same sentence as CCDC77 in open-access papers:
CCDC77 is named in the same sentence as 4 diseases in open-access papers, as found by Europe PMC text mining. Sharing a sentence is not in itself a finding about the gene and the disease. The quoted sentences say what the papers report.
glioma (1 paper, 2024). A benign or malignant brain and spinal cord tumor that arises from glial cells (astrocytes, oligodendrocytes, ependymal cells). "Furthermore, we could identify several novel glioma biomarkers likely helpful in both diagnosis and prognosis of the patients, including the genes PPP1R8, GPBP1L1, KIAA1614, C14orf23, CCDC77, BVES, EXD3, CD300A, and HEPN1." (PMID 38812741, 2024).
cancer (3 papers, 2020 to 2024). A tumor composed of atypical neoplastic, often pleomorphic cells that invade other tissues. "For example, CCDC77 was suggested based on the information on the cancer dependency (DepMap), cancer gene expression, an annotation for the GO term “centriole,” tissue gene expression, and protein interaction with KIAA0753." (PMID 38482491, 2024).
CCDC77 also shares sentences with these, for which no sentence is quoted: astrocytoma (1 paper); male infertility (1).